LMOD2 (leiomodin 2)
Description:
Mediates nucleation of actin filaments and thereby promotes actin polymerization. Plays a role in the regulation of actin filament length (By similarity). Required for normal sarcomere organization in the heart, and for normal heart function.
Synonyms: C-LMOD; CLMOD; CMD2G
Tractability: Small molecule: a structure with a bound ligand is known.
Gene: Protein-coding gene on chromosome 7 (123,655,866 to 123,664,290, forward strand). Ensembl gene ENSG00000170807.
Subcellular location: Cytoplasm, myofibril, sarcomere; Cytoplasm, myofibril; Cytoplasm, myofibril, sarcomere, M line; Cytoplasm, cytoskeleton
Subcellular location (Human Protein Atlas): Plasma membrane; Actin filaments; Cytosol
Gene Ontology:
Molecular function: actin binding; actin monomer binding; tropomyosin binding
Biological process: actin nucleation; positive regulation of actin filament polymerization; sarcomere organization; actin filament organization; muscle contraction; myofibril assembly; actin filament polymerization; pointed-end actin filament capping
Cellular component: actin filament; M band; myofibril; sarcomere; cytoskeleton; striated muscle thin filament
Genetic constraint (gnomAD): Loss-of-function variants: 24 observed, 34.29 expected, observed/expected ratio (o/e) 0.7, 90% interval 0.51 to 0.98. The upper end of that interval is the gene's LOEUF score, 0.98, which puts it in group 4 of 6, group 1 being the genes least tolerant of losing a copy. Missense variants: 615 observed, 648.58 expected, observed/expected ratio (o/e) 0.95, 90% interval 0.89 to 1.01. Synonymous variants: 249 observed, 238.29 expected, observed/expected ratio (o/e) 1.04, 90% interval 0.94 to 1.16.
Gene-disease validity (ClinGen):
ClinGen rates the evidence that LMOD2 causes each of these diseases.
cardiomyopathy, dilated, 2G (autosomal recessive): Definitive.
Homologues: Orthologues: chimpanzee LMOD2 (100% identical), macaque LMOD2 (99% identical), rabbit LMOD2 (93% identical), rat Lmod2 (90% identical), mouse Lmod2 (90% identical), pig LMOD2 (90% identical), guinea pig LMOD2 (87% identical), dog LMOD2 (83% identical), tropical clawed frog lmod2 (66% identical), zebrafish lmod2b (54% identical), zebrafish lmod2a (31% identical). Paralogues in human: LMOD1 (39% identical), LMOD3 (35% identical), TMOD1 (26% identical), TMOD2 (26% identical), TMOD3 (26% identical), TMOD4 (22% identical).
Diseases named in the same sentence as LMOD2 in open-access papers:
LMOD2 is named in the same sentence as 17 diseases in open-access papers, as found by Europe PMC text mining. Sharing a sentence is not in itself a finding about the gene and the disease. The quoted sentences say what the papers report.
dilated cardiomyopathy (6 papers, 2019 to 2024). Cardiomyopathy which is characterized by dilation and contractile dysfunction of the left and right ventricles. "We reported the first known case of a mutation in LMOD2 (p.W398*) that results in severe neonatal dilated cardiomyopathy (DCM)." (PMID 38748723, 2024). "To date, four distinct LMOD2 mutations have been discovered in individuals from five separate families that all present with early onset dilated cardiomyopathy." (PMID 38748723, 2024). "Few reports have implicated homozygous loss of function variants of LMOD2 in neonatal dilated cardiomyopathy (DCM) associated with thin filament shortening." (PMID 37296576, 2023). "Within the leiomodin protein family, Lmod1 is smooth muscle restricted, loss of cardiac Lmod2 induces dilated cardiomyopathy in mice and mutations in Lmod3 can cause nemaline myopathy in humans and mice." (PMID 35148320, 2022). "Mutations in the cardiac predominant isoform, LMOD2 lead to severe neonatal dilated cardiomyopathy." (PMID 38748723, 2024). "The first human mutation in Lmod2 (LMOD2, p.Trp398*) was only recently discovered; this homozygous mutation resulted in undetectable Lmod2 protein expression, extremely short thin filaments, and severe neonatal dilated cardiomyopathy." (PMID 31899774, 2020). "Mutations in the Leiomodin 2 (LMOD2) gene result in a severe form of early-onset dilated cardiomyopathy that, without intervention, leads to death within weeks of birth." (PMID 38748723, 2024). "In this study we discovered that multiple human LMOD2 mutations associated with dilated cardiomyopathy lead to a lack of LMOD2 protein expression through NMD." (PMID 38748723, 2024). "In addition, knocking out the LMOD2 gene can shorten thin filament (actin) prior to dilated cardiomyopathy." (PMID 31600309, 2019). "Using a constitutive Lmod2-knockout mouse model, our laboratory demonstrated that the absence of Lmod2 leads to rapid-onset dilated cardiomyopathy; the observation independently reached in a different study that investigated a transgenic mouse model with a homozygous Lmod2-piggyBac mutation." (PMID 31899774, 2020).
cardiomyopathy (5 papers, 2017 to 2025). A disease of the heart muscle or myocardium proper. "Lmod2-TG mice also exhibit a unique combination of phenotypes associated with cardiomyopathies, such as enlarged atrial and ventricular lumens, increased heart mass and myofibril disarray." (PMID 31899774, 2020). "Our laboratory has recently discovered a direct link between leiomodin-2 and human cardiomyopathy based on a case study of an infant with a homozygous Lmod2 nonsense mutation." (PMID 31899774, 2020). "For example, human LMOD2 mutation W398* (e.g., truncation at residue 398) causes severely reduced expression of LMOD2 due primarily to nonsense mediated decay, abnormally short TFs, and decreased contractile force resulting in cardiomyopathy." (PMID 39883708, 2025). "It is possible to argue that LMOD2 should be included on the cardiomyopathy panel since six cases of similar genotypes and phenotypes provide solid evidence of its pathogenicity." (PMID 37296576, 2023). "Herein, we present the phenotypic and histological features of this variant, confirm the pathogenic impact on protein expression and sarcomere structure, and discuss the current knowledge of LMOD2-related cardiomyopathy." (PMID 37296576, 2023). "Currently, LMOD2 is inconsistently included in congenital to pediatric cardiomyopathy panels." (PMID 37296576, 2023). "The second ranked hub gene for the tissue group including skeletal muscle and heart–left ventricle was LMOD2, which was observed to be abundantly expressed in both tissues and has been reported to regulate the thin filament length in muscles affecting cardiomyopathy in mice." (PMID 29021288, 2017). "In contrast to LMOD3, LMOD2, another member of the LMOD family involved in thin filament shortening and cardiomyopathy, was also up-regulated in Klhl41 KO mice both at protein and mRNA levels." (PMID 28826497, 2017).
heart failure (4 papers, 2020 to 2022). Inability of the heart to pump blood at an adequate rate to meet tissue metabolic requirements. "Whereas LMOD2 is required for the normal sarcomere organization in the heart, cardiac-specific overexpression of Lmod2 led to elongated actin thin filaments, cardiac hypertrophy, interstitial fibrosis, and heart failure." (PMID 35563680, 2022). "One prior study reported that thin filament (F-actin) elongation by the increased expression of Lmod2 resulted in heart failure in a mouse model." (PMID 34681906, 2021).
cardiac hypertrophy (2 papers, 2020 to 2022). "Increased HW/BW and HW/TL values in Lmod2-TG mice are a typical hallmark of cardiac hypertrophy, whereas increased LW/BW and LW/TL values suggest a congested state of Lmod2-TG lungs." (PMID 31899774, 2020).
hypertrophic cardiomyopathy (2 papers, 2012 to 2023). A condition in which the myocardium is hypertrophied without an obvious cause. "Leiomodin 2 is encoded by a gene that is located near the hypertrophic cardiomyopathy locus CMH6 on chromosome 7, suggesting that Lmod2 may be involved in that disease process." (PMID 22901283, 2012).
Ventricular arrhythmia (2 papers, 2016 to 2023). "Two of the four reports suggest that LMOD2 may be associated with ventricular arrhythmias." (PMID 37296576, 2023). "Taken together, our data reveal that Lmod2 is required in heart thin filaments for integrity of sarcomere and ICD and deficient mice exhibit DCM with ventricular arrhythmias and postnatal lethality." (PMID 27274810, 2016).
large artery stroke (1 paper, 2025). Stroke caused by the blockage of blood flow in one of the large arteries feeding the brain. "On the other hand, the 9p21 region, leiomodin 2 (LMOD2), and WASP-like actin nucleation-promoting factor (WASL2) genes have been reported to associate MO with large-artery stroke." (PMID 40724883, 2025).
Stroke (1 paper, 2025). Sudden impairment of blood flow to a part of the brain due to occlusion or rupture of an artery to the brain. "Six days post-stroke, differentially expressed thin filament proteins were annotated as follows: Ablim1, Pdlim1, Lmod2, Dbnl, Parvb, Pdlim3, Tpm2, parvin alpha (Parva), and destrin (Dstn) were upregulated, while Lmod3 was downregulated." (PMID 41226396, 2025).
cardiac disease (1 paper, 2020). "Most, if not all, of our data suggest that the primary effect of excess Lmod2 is elongated thin filaments, and that this alteration leads to cardiac disease progression." (PMID 31899774, 2020).
myopathy (1 paper, 2019). A disease of the muscle in which the muscle fibers do not function properly. "It is worth noting that the expression of LMOD2 in affected chickens increases from week 3 to week 7 suggesting an association with the progression of the WB myopathy." (PMID 31748687, 2019).
LMOD2 also shares sentences with these, for which no sentence is quoted: autism spectrum disorder (1 paper); congenital structural myopathy (1); familial dilated cardiomyopathy (1); laryngeal carcinoma (1); psychosis (1); schizophrenia (1); ventricular dilatation (1).